TOP3B (DNA topoisomerase III beta)
Diseases named in the same sentence as TOP3B in open-access papers (continued):
Sharing a sentence is not in itself a finding about the gene and the disease.
cancer (7 papers, 2016 to 2025). A tumor composed of atypical neoplastic, often pleomorphic cells that invade other tissues. "We would predict those with mutated TOP3B would be likely to develop cancers much later in life, consistent with our patient first diagnosed at 49 years of age." (PMID 31795919, 2019). "This is a very interesting new area and we believe over time TOP3B will be added to the list of causative cancer genes." (PMID 31795919, 2019). "We show TOP3B loss results in excessive R-loop formation, DNA damage and chromosomal instability, and predisposes cells to cancer." (PMID 31795919, 2019). "To determine whether homozygous deletions around the TOP3B gene are enriched in cancer mutation datasets, we examined the frequency in the Catalogue Of Somatic Mutations In Cancer (GRCh38 COSMIC v89, cancer.sanger.ac.uk/cosmic)." (PMID 31795919, 2019). "In parallel, TOP3B is associated with polyribosomes and translating mRNA pools, localizes to RNA stress granules (cytoplasmic membrane-less assemblies of non-translating mRNAs and proteins formed in response to cellular stress) and promotes translation of subsets of RNAs in cancer cells and neurons." (PMID 37980342, 2023). "This identified TOP3B as a putative cancer gene and supports recent data that R loops are involved in cancer aetiology." (PMID 39095811, 2024). "The R-loop suppressing activity of TOP3B also helps during transcription in cancer cells and neuronal activity-dependent transcription in mouse brain tissue." (PMID 37980342, 2023). "Our data show that TOP3B is necessary to prevent the accumulation of excessive R-loops and identify TOP3B as a putative cancer gene, and support recent data showing that R-loops are involved in cancer aetiology." (PMID 31795919, 2019). "Our own bioinformatic analyses show a marked increase in homozygous deletions of TOP3B in a broad range of cancer somatic tissues." (PMID 31795919, 2019). "The biologic role and the prognostic effect of TOP3A and TOP3B in cancer patients are still poorly understood." (PMID 28355294, 2017). "The biologic role of TOP3 remained poorly understood, as well as the prognosis value of TOP3A and TOP3B in cancer patients." (PMID 27315793, 2016). "Top3b-mediated suppression of R-loops regulates transcription in cancer cells and neurons." (PMID 40568167, 2025). "TOP3B deletions were found in a broad range of cancer tissue types." (PMID 31795919, 2019). "However, little is known about R-loops, immune- and cancer-related phenotypes of Top3b-KO mice." (PMID 40568167, 2025). "In addition, Top3b accelerates translation of a group of RNAs both in cancer cells and neurons." (PMID 40568167, 2025). "Survival analysis showed that the CNVs of TOP2B in 13 cancer types, TOP3B in 7 cancer types, TOP2A in 6 cancer types, TOP1MT in 6 cancer types, TOP3A in 5 cancer types and TOP1 in 5 cancer types significantly correlated with overall prognosis." (PMID 36288358, 2022). "It is noteworthy that different topoisomerase family genes may have an up- or down-regulation in the same types of cancer, such as TOP2A and TOP3B in KIRC." (PMID 36288358, 2022). "Why does TOP3B disruption not lead to early onset cancers similar to BTRR subunits disruption?" (PMID 31795919, 2019).
neurological disease (4 papers, 2019 to 2026). "The deletion and mutation of Topoisomerase 3β (TOP3B) is linked to multiple neurological disorders and is the only known topoisomerase that is also catalytically active on RNA in vitro and in cells." (PMID 41815835, 2026). "Locus deletions and de novo point mutations linked to neurological disorders highlight the biological importance of encoding a functional TOP3B." (PMID 41189056, 2025). "Together, these data provide critical new insights into how neurological disease mutations affect TOP3B and how unresolved TOP3B•mRNA covalent intermediates impact neuronal toxicity and translational control." (PMID 41189056, 2025). "Three neurological disease-linked de novo TOP3B point mutations outside of the active site have been identified but their impact on TOP3B activity in cells remains poorly understood." (PMID 41189056, 2025). "Two recent case reports, involving similar TOP3B genomic deletions associated with neurological disorders, have been reported." (PMID 31795919, 2019). "In addition to the more common pathogenic deletion of the TOP3B locus, three de novo point mutations have been reported in individuals presenting with neurological disorders." (PMID 41189056, 2025).
psychiatric disorder (4 papers, 2019 to 2025). A disorder characterized by behavioral and/or psychological abnormalities, often accompanied by physical symptoms. "TBR1 has also been associated with ASD and TCF4 with BPD, and TOP3B was shown to bind multiple mRNAs derived from ASD-linked genes, raising the possibility that STX1A-mediated neurotransmitter release is dysregulated in multiple psychiatric disorders." (PMID 31142819, 2021). "However, our TOP3B-deficient patient displays no mental illness." (PMID 31795919, 2019).
tumor (3 papers, 2016 to 2025). "To gain insight into the molecular mechanisms promoting the tumor predisposition phenotype of Top3b-KO mice, we explored R-loops and the transcriptome of 3-month-old young adult splenocytes." (PMID 40568167, 2025). "Bioluminescence imaging on day 21 showed on average a 3-fold increase in tumor mass in Top3b-KO recipients." (PMID 40568167, 2025). "For TOP3A (0 vs. 6) and TOP3B (0 vs. 2), although limited, all datasets with any expression changes, showed gene downregulation in tumor vs. normal tissues." (PMID 27315793, 2016). "Therefore, potential tumour suppressor or DNA repair genes could be negatively affected in cells without TOP3B." (PMID 31795919, 2019).
TOP3B also shares sentences with these, for which no sentence is quoted: neurodevelopmental disorder (3 papers); 22q11.2 Duplication Syndrome (1); atrial septal defect (1); autism spectrum disorder (1); cognitive disorder (1); colorectal cancer (1); Digeorge Syndrome (1); Hypocalcemia (1); Infertility (1); juvenile myoclonic epilepsy (1); melanoma (1); myeloma (1); peripheral T-cell lymphomas (1); polycystic ovary syndrome (1); pulmonary atresia (1); ventricular septal defect (1).